G6PD (glucose-6-phosphate dehydrogenase)
Diseases named in the same sentence as G6PD in open-access papers (continued):
Sharing a sentence is not in itself a finding about the gene and the disease.
G6PD deficiency (continued). "Socio-demographic data and blood samples were collected and G6PD deficiency was qualitatively detected in fresh blood in the field using the CareStartTM G6PD RDT, while the enzymatic assay was used to quantitatively measure enzyme activity." (PMID 27329471, 2016). "In this work, we review the state of the art in G6PD deficiency, describing 217 mutations in the g6pd gene; we also compile information about 31 new mutations, 16 that were not recognized and 15 more that have recently been reported." (PMID 27941691, 2016). "The drug is known to cause acute haemolytic anaemia in individuals with glucose-6-phosphate-dehydrogenase (G6PD) deficiency." (PMID 27388012, 2016). "As for the severe G6PD deficiency group, the enzyme activity appeared to be reduced also seen after Day 1, but significant drop was detected much earlier as compared to the normal G6PD group." (PMID 27103895, 2016). "Considering the hematopoietic toxicity and carcinogenicity of benzene and G6PD deficiency affecting over 400 million individuals worldwide, we provided novel insights into the protective mechanisms of G6PD-deficient population against benzene poisoning." (PMID 27656260, 2016). "An excess of menadione causes NADPH depletion and glucose-6-phosphate dehydrogenase (G6PD) deficiency." (PMID 26994287, 2016). "This study aimed to evaluate the prevalence and alteration of hematological parameters in malaria patients with a glucose-6-phosphate dehydrogenase (G6PD) deficiency, in the western region of Thailand, an endemic region for malaria." (PMID 27109515, 2016). "The field utility of the CareStartTM G6PD RDT for screening of G6PD deficiency is supported by the finding of a previous study that reported its higher sensitivity compared to the FST when using capillary blood, making it more appropriate for field screening." (PMID 27329471, 2016). "The present study aimed to determine G6PD deficiency among Yemeni children in malaria-endemic areas as well as to assess the performance of the CareStartTM G6PD rapid diagnostic test (RDT) for its detection." (PMID 27329471, 2016). "Glucose-6-phosphate dehydrogenase (G6PD) deficiency is an uncommon inherited enzyme deficiency characterized by hemolytic anemia, caused by the inability of erythrocytes to detoxify oxidizing agents such as drugs, infectious diseases, or fava bean ingestion." (PMID 26435857, 2015). "The CareStart G6PD RDT kit presents as an attractive tool for point-of-care G6PD deficiency testing in areas with high temperatures and requires significantly less time and training to implement." (PMID 25885097, 2015). "G6PD deficiency (G6PDd) is the result of a structural defect of the G6PD enzyme and is one of the most common enzymopathies worldwide." (PMID 26416229, 2015). "In this study, we systematically evaluated the prevalence of G6PD deficiency in the Kachin (Jingpo) ethnic group along the China-Myanmar border and determined the underlying G6PD genotypes." (PMID 26226515, 2015). "Comparing the performance of CareStart G6PD RDT kit by gender to routinely used methods to screen for G6PD deficiency." (PMID 25885097, 2015). "Glucose-6-phosphate dehydrogenase (G6PD) deficiency is associated with erythrocyte sensitivity to oxidative damage and hemolytic crises." (PMID 26688730, 2015). "Of the 16,464 samples that were screened, 672 were positive for G6PD deficiency, as assessed by the G6PD/6PGD ratios using the spectrophotometer method, and included 377 females and 295 males." (PMID 25775246, 2015). "Based on the experience in G6PD deficient African American soldiers, radical cure with primaquine was long considered safe; however, the potential risks in more severe variants of G6PD deficiency can be considerable." (PMID 26416229, 2015). "We surveyed G6PD deficiency in 1770 adult individuals (671 males and 1099 females) of the Kachin ethnicity using a G6PD fluorescent spot test." (PMID 26226515, 2015).
G6PD deficiency (continued). "Main objectives of the workshop were on the challenges and evidence gaps facing successful implementation of G6PD screening in the context of currently available and anticipated point-of-care tests for G6PD deficiency." (PMID 26416229, 2015). "Although dapsone induced hemolytic anemia is mostly reported in patients with G6PD deficiency, there are reports of dapsone induced hemolytic anemia in literature regarding transplant recipients who have normal G6PD levels." (PMID 25628986, 2015). "The overall prevalence of G6PD deficiency was 19.3% (291/1507); 2.3% G6PD full defect and 17.0% G6PD partial defect." (PMID 26327623, 2015). "Glucose-6-phosphate dehydrogenase (G6PD) deficiency and hemoglobinopathies were the inherited conditions found mostly in African." (PMID 25915902, 2015). "Epidemiologists and geneticists eventually surveyed the diversity of G6PD deficiency, finding Africa and the Americas to be relatively homogeneous; the A − variant dominated among the G6PD-deficient people on those continents." (PMID 25943156, 2015). "At present, the 8-aminoquinoline primaquine is the only drug recommended by the World Health Organization (WHO) to treat P. vivax hypnozoites, but it is contraindicated in subjects with severe glucose-6-phosphate dehydrogenase (G6PD) deficiency." (PMID 25385861, 2015). "A maximum of 1.6ml of capillary blood samples were used for G6PD deficiency screening using CareStart G6PD RDT and Trinity qualitative with Trinity quantitative methods as the “gold standard”." (PMID 25885097, 2015). "Inaccurate high cutoff values to define G6PD deficiency in the spectrophotometric analysis would underestimate the sensitivity of the BinaxNOW G6PD." (PMID 25385861, 2015). "The results from this study suggest that the diagnostic performance of the CareStart G6PD RDT is acceptable at determining the G6PD deficiency status in a high malaria endemic area in Ghana, Africa." (PMID 25885097, 2015). "A rapid and inexpensive methods to determine the G6PD status of all persons is desirable when one is considering use of drugs contraindicated in patients with G6PD deficiency." (PMID 25885097, 2015). "Oxidant hemolysis, caused by dapsone’s metabolite hydroxylamine, is a common side effect, and screening for glucose-6-phosphate dehydrogenase (G6PD) deficiency is recommended before the drug is started in order to prevent potential hemolytic reactions." (PMID 25628986, 2015). "G6PD deficiency is caused by X-linked, hereditary mutations in the G6PD gene, which result in protein variants with different levels of enzyme activity that are related to a wide range of biochemical and clinical phenotypes." (PMID 25775246, 2015). "While the precise causal mechanism between G6PD deficiency and hyperbilirubinemia is not yet fully understood, early detection of G6PD deficient infants is essential to effectively manage the risk of severe hyperbilirubinemia in the affected infants." (PMID 25675342, 2015). "Malaysia provides in-patient care to P. vivax malaria patients and 14 days of 0.25 mg/kg bw primaquine is provided to people with intermediate FST results (mild G6PD deficiency) compared to the 0.5 mg/kg bw to G6PD normal patients." (PMID 26416229, 2015). "The only hypnozoitocide available is primaquine, a drug causing life-threatening acute hemolytic anemia in patients with the inherited blood disorder glucose-6-phosphate dehydrogenase (G6PD) deficiency." (PMID 26652887, 2015). "Understanding the participation of G6PD in NET release is clinically important because G6PD deficiency is the most common enzyme deficiency worldwide, affecting more than 400 million people." (PMID 26198639, 2015). "In those regions residents mostly carry variants of G6PD deficiency considered ‘severe’, that is, relatively very low residual G6PD enzyme activity." (PMID 25943156, 2015).
G6PD deficiency (continued). "Glucose-6-phosphate dehydrogenase (G6PD) deficiency is an X-linked hereditary disease that predisposes red blood cells to oxidative damage." (PMID 26226515, 2015). "We have shown that G6PD modulates the secretion of the pro-inflammatory cytokine IL-8 via oxidative stress and NF-κB pathway because the elevated IL-8 due to G6PD deficiency is partially blocked by exogenous antioxidant and NF-κB inhibitors." (PMID 25945076, 2015). "To determine the genetic basis of G6PD deficiency in the study population, we selected 198 unrelated G6PD-deficient subjects (51 males and 147 females) for genotyping 11 common mutations occurring in Southeast Asia using a recently developed SNaPshot assay." (PMID 26226515, 2015). "G6PD deficiency is a common disorder and many other widely used drugs can cause haemolysis in G6PD deficient individuals." (PMID 26416229, 2015). "Conversely, the risks of severe malarial anaemia in G6PD c.202T hemizygous boys and homozygous girls with G6PD deficiency were significantly higher." (PMID 26686045, 2015). "The diagnostic accuracy of CareStart G6PD RDT to screen for G6PD deficiency when compared to Trinity biotech qualitative (P = 0.124) and Trinity biotech quantitative (P = 0.123) method were not significantly affected by gender." (PMID 25885097, 2015). "A recent study conducted in The Gambia, found that another variant, G6PD Betica (T968C/A376G), was the most common cause of G6PD deficiency in that part of continent, which suggested a regional genotypic difference of G6PD deficiency in Africa." (PMID 25915902, 2015). "The rate of the C1311T/IVS polymorphism in 469 individuals with G6PD deficiency was 13.9% (65 of 469), and all the 22 male patients with G6PD Viangchan had the C1311T/IVS polymorphism." (PMID 25775246, 2015). "The up-regulation of IL-8 caused by G6PD deficiency in HepG2 cells was confirmed in other G6PD-deficient cells by qRT-PCR." (PMID 25945076, 2015). "The data presented here confirms that the A(−) G6PD allele can result in severe G6PD deficiency (< 10% normal activity), even if it is currently classified as a class III G6PD variant." (PMID 25071003, 2014). "Protein stability has been extensively studied in human G6PD, and it has already been demonstrated that several mutations can induce G6PD deficiency by decreasing its stability." (PMID 25407525, 2014). "The wide-scale use of primaquine is hampered by its hemolytic effect in people with glucose-6-phosphate dehydrogenase (G6PD) deficiency." (PMID 24913169, 2014). "Nigeria is frequently associated with disproportionately high rates of severe neonatal jaundice (NNJ) underpinned by widespread Glucose-6-phosphate dehydrogenase (G6PD) deficiency." (PMID 24774506, 2014). "Persistent P. vivax liver stages can be eliminated only by radical treatment with a ≥ seven-day course of an 8-aminoquinoline, with the attendant risk of acute haemolytic anaemia in individuals with glucose-6-phosphate dehydrogenase (G6PD) deficiency." (PMID 24502194, 2014). "G6PD deficiency is of interest because primaquine-induced hemolysis increases in the presence of G6PD variants." (PMID 24853873, 2014). "Glucose-6-phosphate dehydrogenase (G6PD) deficiency is associated with protection from severe malaria, and potentially uncomplicated malaria phenotypes." (PMID 25015414, 2014). "It has been documented that G6PD deficiency in sub-Saharan Africa is due to the 202A/376G G6PD A-allele, and association studies have used genotyping as a convenient technique for epidemiological studies." (PMID 25015414, 2014). "Venous blood was collected for microscopy and screening for Glucose 6-phosphate dehydrogenase (G6PD) deficiency." (PMID 24624240, 2014). "Despite the low cytotoxicity of Phe-Ala-PQ, one of the serious and limiting problems of PQ derivatives is their hematological toxicity, mainly in patients with the glucose-6-phosphate dehydrogenase (G6PD) deficiency." (PMID 25133630, 2014).
G6PD deficiency (continued). "How do other malaria-protective polymorphisms, such as type O blood group antigen and glucose-6-phosphate dehydrogenase (G6PD) deficiency, interact with iron deficiency in mitigating malaria pathogenesis?" (PMID 24834053, 2014). "This requires radical treatment course of primaquine therapy, an 8-aminoquinoline anti-malarial drug, which causes dose-dependent acute haemolytic anaemia (AHA) of varying severity in individuals with glucose-6-phosphate dehydrogenase (G6PD) deficiency." (PMID 24502194, 2014). "The prevalence of Glucose-6-Phosphate Dehydrogenase (G6PD) deficiency is estimated to be 8% in Afghanistan which complicates the use of the reccomended 14 day regiment of primaquine (PQ) for P.vivax." (PMID 25033452, 2014). "Glucose-6-phosphate dehydrogenase deficiency is an X-linked recessive hereditary disease characterised by abnormally low levels of G6PD." (PMID 24943486, 2014). "With a relatively high prevalence of G6PD deficiency in Madina, testing for G6PD should be an important pre-requisite for antimalarial treatment including IPTp." (PMID 24624240, 2014). "The prevalence and likely severity of G6PD deficiency varied, but certainly the majority of G6PD deficient individuals in Afghanistan would have had the Mediterranean variant, which is associated with severe haemolytic reactions following primaquine." (PMID 24502194, 2014). "Two commercialized test kits (Trinity G-6-PDH and CareStart G6PD test) were used for G6PD deficiency screening." (PMID 24853873, 2014). "A quantitative model of P. vivax transmission will allow for the benefits of primaquine treatment to be weighed against the risks of G6PD deficiency and the costs of G6PD testing." (PMID 25406065, 2014). "Our results suggest that multiple alleles at the G6PD locus play a role in determining G6PD deficiency state and therefore merit consideration in genetic association studies of clinical phenotypes such as severe malaria or drug sensitivity." (PMID 25201310, 2014). "8-Aminoquinoline–based drugs clear the parasite; however, people with glucose-6-phosphate dehydrogenase (G6PD) deficiency are at risk for hemolysis from these drugs." (PMID 25071003, 2014). "FS test detected G6PD deficiency in only 22% (8/36) of female adults with G6PD Viangchan mutation, while MR test detected G6PD deficiency in 42% (15/36)." (PMID 23965028, 2013). "In tropical Africa, the G6PD A- variant is thought to account for 90% of G6PD deficiency, with about 90% of G6PD A- resulting from the G6PD202A,376G allele." (PMID 23874768, 2013). "The WHO has endorsed 5 methods as screening or diagnostic tests for G6PD deficiency including quantitative measurement of G6PD activity in red blood cells (RBCs)." (PMID 24016342, 2013). "Rapidly ascertaining the G6PD status of a person is desirable when one is considering use of a drug contra-indicated in patients with G6PD deficiency." (PMID 23965028, 2013). "As early as the 1960s, Frank B. Livingstone started assembling a global database of the frequencies of hemoglobin variants, thalassemias, glucose-6-phosphate dehydrogenase deficiency, G6PD variants, and ovalocytosis in human populations." (PMID 23568771, 2013). "It is crucial to determine the 60% cut-off point for mean normal residual G6PD activity to diagnose G6PD deficiency and determine the 10 to 60% range to establish partial deficiency." (PMID 23965028, 2013). "This study assessed the prevalence and genotype of G6PD deficiency in Afghan populations and examined the need for routine G6PD testing as a malaria treatment and control tool." (PMID 23834949, 2013). "Glucose-6-phosphate dehydrogenase deficiency (G6PD), an x-linked inherited enzymopathy, is a barrier to malaria control because primaquine cannot be readily applied for radical cure in individuals with the condition." (PMID 23834949, 2013).
G6PD deficiency (continued). "Upgrades of the CareStart® G6PD deficiency screening test are in development including a version which allows quantitative estimate of G6PD activity using a reader." (PMID 23537118, 2013). "Infants with G6PD deficiency needed significantly longer phototherapy treatment than those who had normal G6PD activity (a median of 49 hours compared with 24 hours, p=0.001)." (PMID 23991145, 2013). "Some reported LRLs/LDLs have been estimated from small sample sizes, from populations with high G6PD deficiency prevalence, and from mixtures of G6PD-normal and G6PD-deficient preterm and full-term neonates." (PMID 24016342, 2013). "Glucose-6-phosphate dehydrogenase (G6PD) deficiency is the most common human enzymopathy and in Sub-Saharan Africa, is a significant cause of infection- and drug-induced hemolysis and neonatal jaundice." (PMID 23874768, 2013). "In order to inform decision making on the need for G6PD testing in the health system, a cross-sectional study was undertaken to estimate the prevalence of G6PD deficiency in the population and to characterize the G6PD deficiency variants." (PMID 23834949, 2013). "Glucose-6-phosphate dehydrogenase (G6PD) deficiency is particularly prevalent in historically malaria-endemic countries." (PMID 23965028, 2013). "Other underlying diseases among the cases group were Behcet’s disease and glucose-6-phosphate dehydrogenase (G6PD) deficiency (1 patient each)." (PMID 24086734, 2013). "Currently two chromatographic test are licensed and commercially available: BinaxNow® G6PD test and CareStart® G6PD deficiency screening test, the latter introduced more recently." (PMID 23537118, 2013). "Analysis of the 937 blood samples for G6PD deficiency revealed two subjects (0.2%) with deficient G6PD." (PMID 23363768, 2013). "Hypocholesterolaemia has also been described in various haematological diseases, including thalassaemia major, thalassaemia intermedia, sickle cell disease, glucose-6-phosphate dehydrogenase (G6PD) deficiency, spherocytosis, and aplastic anaemia." (PMID 24314058, 2013). "The drug has scarcely been used in Africa because of concerns about its safety in people with glucose-6-phosphate dehydrogenase (G6PD) deficiency." (PMID 23130957, 2012). "In females who are carriers of a mutant G6PD haplotype, mosaic expression of G6PD on the affected X chromosome due to skewed X-inactivation can lead to clinical G6PD deficiency." (PMID 23006493, 2012). "In this study, a low prevalence of G6PD deficiency was found: G6PD (A-) patients represented a proportion of 0.85%." (PMID 23057857, 2012). "We studied a small population of G6PD deficiency infants but nevertheless G6PD c.563C > T was observed as an important risk factor for early development and moderately severe hyperbilirubinemia in neonates." (PMID 22906047, 2012). "The prescription of primaquine to all malaria cases without prior testing for G6PD deficiency presents a potential risk for severe haemolytic anaemia in G6PD-deficient patients, although G6PD deficiency is an infrequent trait in Guyana." (PMID 23083017, 2012). "In this communication, we report the results of a 6-locus haplotypic analysis of the G6PD gene in Saudi patients suffering from G6PD deficiency." (PMID 23006493, 2012). "Screening of G6PD deficiency by using blood spots among the malaria infected cases gave results which were considered skewed towards artificially low G6PD enzyme activity levels due to methodical problems, as explained in the discussion section." (PMID 23049687, 2012). "Another prevalent genetic disorder in previous and present malarious areas is glucose-6-phosphate-dehydrogenase (G6PD) deficiency." (PMID 23057857, 2012). "The striking concordance between the areas where G6PD deficiency is common and those where Plasmodium falciparum malaria is endemic provides circumstantial evidence that G6PD deficiency confers resistance against malaria." (PMID 23006493, 2012).